Y_RNA (Y RNA )
Gene: Miscellaneous RNA gene on chromosome 3 (184,086,791 to 184,086,903, reverse strand). Ensembl gene ENSG00000207351.
Homologues: Orthologues: chimpanzee Y_RNA (97% identical), macaque Y_RNA (93% identical), mouse Gm56393 (73% identical). Paralogues in human: RNY1 (88% identical), Y_RNA (85% identical), RNY1P2 (84% identical), Y_RNA (84% identical), Y_RNA (83% identical), RNY1P11 (82% identical), RNY1P8 (82% identical), Y_RNA (82% identical), Y_RNA (81% identical), RNY1P7 (80% identical), Y_RNA (80% identical), RNY1P10 (79% identical), and 98 more.